EMCN (endomucin)
Description:
Endothelial sialomucin, also called endomucin or mucin-like sialoglycoprotein, which interferes with the assembly of focal adhesion complexes and inhibits interaction between cells and the extracellular matrix.
Synonyms: EMCN2; MUC14
Tractability: Antibody: UniProt places it where antibodies can reach, with high confidence; UniProt predicts a signal peptide or a membrane-spanning region; its Gene Ontology location is reachable by antibodies, with medium confidence.
Gene: Protein-coding gene on chromosome 4 (100,395,341 to 100,880,126, reverse strand). Ensembl gene ENSG00000164035.
Subcellular location: Cell membrane (Isoform 1); Membrane; Secreted (Isoform 2)
Gene Ontology:
Cellular component: extracellular region; membrane; plasma membrane
Genetic constraint (gnomAD): Loss-of-function variants: 16 observed, 17.93 expected, observed/expected ratio (o/e) 0.89, 90% interval 0.6 to 1.36. The upper end of that interval is the gene's LOEUF score, 1.36, which puts it in group 5 of 6, group 1 being the genes least tolerant of losing a copy. Missense variants: 159 observed, 169.21 expected, observed/expected ratio (o/e) 0.94, 90% interval 0.82 to 1.07. Synonymous variants: 41 observed, 56.56 expected, observed/expected ratio (o/e) 0.72, 90% interval 0.56 to 0.94.
Homologues: Orthologues: chimpanzee EMCN (98% identical), macaque EMCN (86% identical), dog EMCN (61% identical), rabbit EMCN (60% identical), mouse Emcn (53% identical), pig EMCN (52% identical), rat Emcn (52% identical).
Diseases named in the same sentence as EMCN in open-access papers:
EMCN is named in the same sentence as 46 diseases in open-access papers, as found by Europe PMC text mining. Sharing a sentence is not in itself a finding about the gene and the disease. The quoted sentences say what the papers report.
breast carcinoma (6 papers, 2019 to 2022). "Breast cancer cells localized in close proximity to Endomucin-positive vascular cells as well as to osteoblasts." (PMID 32272947, 2020). "Since single breast cancer cells localize not only close to osteoblasts but also nearby Endomucin-positive vascular endothelial cells, we investigated potential alterations of the bone marrow vasculature in non-tumor cell-bearing tibiae from Tgif1+/+ and Tgif1−/− mice." (PMID 32272947, 2020). "To further investigate the clinical significance of EMCN expression in metastatic lung and breast cancer patients, we analyzed EMCN expression in patients with and without metastasis." (PMID 36184589, 2022).
lung carcinoma (5 papers, 2019 to 2023). "To further validate our experimental results, we examined the clinical significance of Notch1 and EMCN in lung cancer by analyzing TCGA dataset." (PMID 36184589, 2022). "The role of EMCN in cancer has still remained controversial, as EMCN is highly expressed in lung cancer, whereas is downregulated in a primary central nervous system lymphoma." (PMID 31803620, 2019). "The downregulation of endomucin (EMCN), a transmembrane protein expressed on the surface of the endothelium, significantly correlates with metastasis and tumor recurrence in lung cancer patients." (PMID 37887354, 2023). "Our analysis also identified four highly significant differentially expressed genes in lung cancer, namely, MIF, CLEC3B, FCN3, and EMCN." (PMID 37359381, 2023). "Our analysis identified four highly significant differentially expressed genes in lung cancer, comprising MIF, CLEC3B, FCN3, and EMCN." (PMID 37359381, 2023).
gastric cancer (4 papers, 2020 to 2021). A primary or metastatic malignant neoplasm involving the stomach. "Therefore, we propose that an EMCN/MUC15 combination could be a potential prognostic signature for gastric cancer." (PMID 32175327, 2020). "MUC14, also known as endomucin (EMCN), is an endothelial sialomucin that inhibits endothelial–leukocyte interaction and has been reported to be a poor prognosis marker in gastric cancer." (PMID 33182511, 2020).
clear cell renal cell carcinoma (3 papers, 2021 to 2025). "Ultimately, by integrating the single-cell RNA sequencing (scRNA-seq) data of clear cell renal cell carcinoma (ccRCC), we discovered that endomucin (EMCN) was linked to endothelial cell differentiation and suppressed the proliferation of ccRCC cells." (PMID 40535574, 2025).
colorectal cancer (3 papers, 2020 to 2022). A primary or metastatic malignant neoplasm that affects the colon or rectum. "overexpression of EMCN induced colorectal cancer proliferation and metastasis both in vitro and in vivo experiments." (PMID 35971319, 2022). "Tumor‐derived endomucin promotes colorectal cancer proliferation and metastasis." (PMID 35971319, 2022). "For example, whether EMCN defects in the liver provide a favorable premetastatic niche for the liver metastasis of mouse colorectal cancer cells warrants further study using a liver metastasis model of colorectal cancer." (PMID 36184589, 2022).
adenoma (2 papers, 2013 to 2020). A neoplasm arising from the epithelium. "When the differential genes in fast‐ and slow‐growing adenomas were confirmed by RNA sequencing analysis and qPCR, the results showed that the expression of endomucin was negatively correlated with tumor volume doubling time." (PMID 33532708, 2020). "We confirmed that ELMO1, EMCN, ITIH5, KCNAB1, and SLCO2A1 were downregulated in follicular carcinoma compared to adenoma." (PMID 24099521, 2013). "Functionally, knocking down endomucin does not affect the migration of adenoma cells in vitro." (PMID 33532708, 2020).
melanoma (2 papers, 2022 to 2023). A malignant, usually aggressive tumor composed of atypical, neoplastic melanocytes. "However, it is unclear whether abnormal angiogenesis in the melanoma bone microenvironment is associated with endomucin expression levels via Hh signaling." (PMID 37240209, 2023). "Future extensive studies should determine the value of EMCN expression as a potential prognostic biomarker in patients with melanoma and other highly metastatic cancers." (PMID 36184589, 2022). "Endomucin is a type I integral membrane glycoprotein expressed apically by capillary and venous endothelial cells, and it accounts for most of the vascular networks formed in melanoma tumor masses." (PMID 37240209, 2023). "However, the variation in the number of HEV cells involved in lymphocytic infiltration of melanoma in the bone microenvironment and their localization with endomucin-positive cells is not clear and is a subject for future studies." (PMID 37240209, 2023).
rheumatoid arthritis (2 papers, 2020 to 2023). A chronic, systemic autoimmune disorder characterized by inflammation in the synovial membranes and articular surfaces. "Endomucin was found to be associated with rheumatoid arthritis in a Japanese population, and the endomucin allele associated with rheumatoid arthritis susceptibility may also be involved in the pathogenesis of rheumatoid arthritis." (PMID 33532708, 2020). "Finally, several genes (SEMA7A, CSK, GUCY1A2, EMCN, OPRM1) are associated with rheumatoid arthritis (RA)." (PMID 36658473, 2023).
amebiasis (1 paper, 2025). A parasitic infectious disorder caused by amoebas. "In this study, the differential genes EMCN and SYT12 have a fold change of ≥2.00 and Padj ≤ 0.05, and 2145 genes annotated to KEGG are significantly enriched in four pathways: the PI3K-Akt signaling pathway, focal adhesion, amebiasis, and the cancer pathway, in this order." (PMID 40428424, 2025).
bone fracture (1 paper, 2025). "Type H blood vessels, distinguished by their high expression of endomucin and CD31, are typically found in the growth plate and metaphysis, where they play a crucial role in both bone development and repair and are known to develop in bone fractures." (PMID 40538272, 2025).
Bone tumors (1 paper, 2023). "We found that mice with ER-expressing E0771/Bone-derived tumors had significantly increased percentages of Sca-1-positive HSCs (64.4-fold increase) and endomucin-positive vasculature (2.8-fold increase) within the bone marrow when compared with TN E0771/Bone tumors." (PMID 38136319, 2023).
breast tumors (1 paper, 2022). "We found that EMCN is specifically expressed in microvascular endothelial cells and showed remarkable downregulation in the majority of both metastatic lung and breast tumors." (PMID 36184589, 2022).
diabetic retinopathy (1 paper, 2021). "Loss of EMCN, for example, has been suggested to be associated with diabetic retinopathy and the overexpression of EMCN leads to the restoration of the glycocalyx and the related EC function in streptozotocin-induced diabetic rats." (PMID 34532323, 2021).
dilated cardiomyopathy (1 paper, 2024). Cardiomyopathy which is characterized by dilation and contractile dysfunction of the left and right ventricles. "Interestingly, EMCN (Endomucin, 608350), which has previously been shown to be associated with hypertrophic cardiomyopathy, was predicted to be associated with dilated cardiomyopathy using such a method, supported by another publication." (PMID 39202774, 2024).
glioma (1 paper, 2020). A benign or malignant brain and spinal cord tumor that arises from glial cells (astrocytes, oligodendrocytes, ependymal cells). "Moreover, the transcription of CD34, EMCN (another marker of endothelial tumor cells) and CD248 was increased in the GBMwt_hi group compared to the rest of gliomas." (PMID 33147752, 2020).
ischemic stroke (1 paper, 2025). A stroke disorder caused by obstruction of blood flow to the brain, due to thrombotic (local blood clot formation) or embolic (due to a blood clot or other material traveling from another site) event. "Since increased endomucin expression would be indicative of angiogenesis, the lack of change in endomucin-expressing endothelium further supports that ischemic stroke stimulated arteriogenesis rather than angiogenesis." (PMID 39896107, 2025).
liver disease (1 paper, 2023). "Capillarization of LSEC is commonly observed in liver disease and is well known to be accompanied by the downregulation of LSEC-characteristic transmembrane proteins such as CD32b and Lyve-1 and the upregulation of proteins characteristic of continuous EC such as Endomucin (Emcn)." (PMID 37446152, 2023).
metastatic tumors (1 paper, 2022). "The results showed that EMCN expression was significantly reduced in metastatic tumors and was strongly reduced in tumor recurrence." (PMID 36184589, 2022).
Osteopenia (1 paper, 2017). Osteopenia is a term to define bone density that is not normal but also not as low as osteoporosis. "Here we tested whether the type H vessel, which was recently identified as strongly positive for CD31 and Endomucin (CD31hiEmcnhi) in mice, is an important indicator of aging and osteopenia in human subjects." (PMID 28471445, 2017).
osteoporosis (1 paper, 2022). A condition of reduced bone mass, with decreased cortical thickness and a decrease in the number and size of the trabeculae of cancellous bone (but normal chemical composition), resulting in increased fracture incidence. "A total of 27 target proteins were obtained, including CD31, EMCN, VEGF, AT1, AT2, ACE, and HIF-1a, all of which are involved in the pathological process of osteoporosis and bone loss and are the target proteins on which MQEP produces a marked effect." (PMID 36147560, 2022).
skin tumor (1 paper, 2013). "Further, although IL-6 signaling promotes skin tumor growth and angiogenesis in a paracrine fashion, we did not detect any difference between KrasG12D and KrasG12D; IL-6-/- mice after immunohistochemical staining with Endomucin, a microvessel density marker to measure angiogenesis index." (PMID 24260500, 2013).
Stroke (1 paper, 2025). Sudden impairment of blood flow to a part of the brain due to occlusion or rupture of an artery to the brain. "The area of endomucin-expressing cells, relative to total area, was similar between stroke and sham groups (p = 0.43) and between exercise and sedentary groups (p = 0.54)." (PMID 39896107, 2025).
tumor (61 papers, 2002 to 2026). "We found that HuR tumor cell loss significantly decreased the presence of endothelial cells, as indicated by the endothelial cell marker endomucin." (PMID 40814996, 2025). "Furthermore, we demonstrate that EMCN deficiency leads to the formation of a premetastatic niche to promote tumor metastasis in a neutrophil-dependent manner." (PMID 36184589, 2022). "We found a strong correlation of EMCN deficiency with tumor recurrence and metastasis." (PMID 36184589, 2022). "Interestingly, in VCaP tumors, endomucin-positive cells surround tumor areas and associated to the bone-forming surfaces, whereas the intra-tumoral regions were devoid of endomucin immunoreactivity." (PMID 29988965, 2018). "To examine the effects of blocking tumor-derived CSF-1 on TMEM doorway activity, we stained the tumor tissue for endomucin and TMR-Dextran and measured the amounts of extravascular dextran compared to the vascular area." (PMID 40646332, 2025). "The CCK-8 assay results revealed that overexpression of EMCN inhibited the proliferation of 786-O and Caki-1 cells, confirming the role of EMCN as a tumor suppressor in ccRCC." (PMID 40535574, 2025). "Tumour sections were stained with antibodies to enable visualisation of CD8+ T cells (CD8+) and blood vessels (Endomucin+) given that some cDC1s have been reported to locate close to perivascular niches in tumours." (PMID 40745918, 2025). "When B16 cells were inoculated into the tibial metaphysis, abundant endomucin-expressing endothelial cells in tumor tissue were observed in the bone marrow." (PMID 37240209, 2023). "Immunohistochemical staining with anti-endomucin and anti-podoplanin antibodies showed reduced tumor angiogenesis and lymphangiogenesis, respectively, in SAP30-KO mice." (PMID 37655663, 2023). "An immunohistochemical analysis of the effect of GANT61 on tumor angiogenesis was thus conducted, using the endothelial marker, endomucin, in the tumor bone microenvironment." (PMID 37240209, 2023). "An intraperitoneal administration of GANT61 (40 mg/kg), a small-molecule inhibitor of Gli1 and Gli2, resulted in significant inhibition of cortical bone destruction, TRAP-positive osteoclasts within the cortical bone, and endomucin-positive tumor vessels." (PMID 37240209, 2023). "The results of the subcutaneous tumor model experiment showed that the tumor volume growth rate in the EMCN overexpression group was considerably higher than that in the control group." (PMID 35971319, 2022). "To explore how EMCN regulates vascular permeability in vivo, we further detected changes in ZO-1 and Claudin5 in the lungs of WT and EMCNecko tumor-bearing mice." (PMID 36184589, 2022). "While laminin (TRITC) was colocalized with endomucin (FITC) in a large fraction of PyMT1 tumor vessels, it was severely impaired in GPx2 KD tumors, with fewer vessels staining for both markers." (PMID 35193955, 2022). "We established a syngeneic mouse model of endothelial cell-specific knockout of EMCN (EMCNecko) to study the role of EMCN in tumor growth and metastasis." (PMID 36184589, 2022). "As a preliminary test, we took tissue sections from the lungs of the EM and SM models and stained them for GFP (to identify tumor cells), MenaINV, endomucin (to identify the vasculature), and DAPI (to identify all nuclei)." (PMID 35110548, 2022). "This was shown by dramatically reduced tumor cell proliferation (Ki67) (first panels), angiogenesis (endomucin) (second panels), ROS-induced DNA damage (8-OxodG) (third panels), and hypoxia (CA-IX) (fourth panels)." (PMID 35193955, 2022). "Tumor cell metastasis typically occurs in small capillaries, and EMCN is a glycoprotein expressed in endothelial cells of these capillaries." (PMID 36184589, 2022). "The levels of EMCN expression were significantly correlated with tumor differentiation (p = 0.007), N classification (p = 0.001), clinical stage (p = 0.006), and distant metastasis (p < 0.001)." (PMID 35971319, 2022).
tumor (continued). "We present a new translational strategy of EMCN as a new key player in tumor lung metastasis by affecting the host microenvironment." (PMID 36184589, 2022). "Immunofluorescence imaging of endomucin+ tumor blood vessels verified that our tamoxifen regimen effectively silenced target expression." (PMID 36970722, 2022). "To further understand the mechanism of endothelial EMCN in tumor metastasis, we constructed a stable EMCN knockdown cell line in vitro." (PMID 36184589, 2022). "During the experiment, one mouse in the overexpression group died because of excessive tumor load; however, only five mice in the EMCN‐knockdown group grew slow‐growing tumors." (PMID 35971319, 2022). "By comparing EMCN expression levels in naive, premetastatic and metastatic lung tissue, we found that EMCN expression levels were decreased significantly in tumor metastasis." (PMID 36184589, 2022). "Pharmacological inhibition of Notch improved EMCN expression, inhibited tumor metastasis, and showed additive effects when combined with anti-TGF-β antibody therapy." (PMID 36184589, 2022). "Despite being described as an endothelial marker, we mainly observed a MUC14/EMCN staining in tumor cells." (PMID 33182511, 2020). "Immunofluorescence staining of the bone marrow vasculature using the endothelial cell marker Endomucin and the osteoblast marker Osterix revealed that tumor cells preferentially localize in close proximity to both vessels and osteoblasts." (PMID 32272947, 2020). "We also found that the percentage of Vegf-a-expressing Ocys positively correlated with Endomucin (EMCN) positive tumor vessel area in our 5TGM1-bearing bones." (PMID 33057033, 2020). "The expression of endomucin is increased after endothelial cell proliferation or tumor conditioned media stimulation." (PMID 33532708, 2020). "Endomucin, a vascular endothelial marker, staining for determining tumour microvessel density demonstrated a 21% decrease with NPT+Gem, 60% decrease with αMMP9 and 65% decrease with NPT+Gem+αMMP9 therapy." (PMID 30941918, 2019). "To confirm the anti-angiogenic mechanism of rTSR1 in mouse tumor suppression, we performed double immunostainings of endomucin/PCNA and endomucin/cleaved caspase-3 to detect proliferating and apoptotic tumor endothelial cells, respectively." (PMID 29891754, 2018). "Blood vessel density (number of endomucin‐positive vessels per mm2 of age‐matched, size‐matched tumour sections) was unchanged between B16F0 tumours grown in ECCre−;FAKWT/WT and ECCre+;FAKWT/WT mice." (PMID 28444899, 2017). "Immunohistochemical analysis of end‐stage midline tumour sections indicated lower endomucin‐positive blood vessel densities in ECCre+;FAKKD/KD and ECCre+;FAKDM/DM mice than in ECCre−;FAKKD/KD and ECCre−;FAKDM/DM mice, respectively." (PMID 28444899, 2017). "Immunohistochemical staining for the endothelial marker endomucin revealed a significant decrease in tumor angiogenesis and vessel count in both the dual LOX/LOXL2 inhibitor treated mice (PXS-S1A) and the LOXL2 specific inhibitor treated mice (PXS-S2B)." (PMID 28199967, 2017). "Later on, we visualized hypoxic regions in these tumor sections in combination with the immunolocalization of Endomucin-positive vessels." (PMID 27120788, 2016). "ELTD1 and EMCN are TM proteins located on cytoplasmic membrane and function in tumour migration and angiogenesis." (PMID 26710964, 2016). "First, we approached single staining of paraffin embedded tumor sections with an antibody against the endothelial marker Endomucin." (PMID 27120788, 2016). "Tumor angiogenesis and lymphangiogenesis were examined by staining primary tumor sections with the panendothelial cell marker endomucin and the lymphatic specific marker podoplanin." (PMID 25924234, 2015). "Prior to immunoblotting, we noticed that the 786-O tumor vascular density appeared to be less than that of normal organs despite its hypervascularity in tissue sections stained with a CD31/endomucin cocktail." (PMID 24376772, 2013).